EGF (epidermal growth factor)
Diseases named in the same sentence as EGF in open-access papers (continued):
Sharing a sentence is not in itself a finding about the gene and the disease.
lung adenocarcinoma (continued). "We observed a remarkable upregulation of the ADAM, EGF, and MMP-7 protein levels in lung adenocarcinoma, while after the SH intervention, these conditions were significantly reversed." (PMID 41444284, 2025). "The downregulation of angulin-1/LSR induces malignancy via the upregulation of EGF-dependent CLDN-2 and cell metabolism via TGF-β signaling that induces EMT in lung adenocarcinoma." (PMID 38338691, 2024). "In the present study, we found that downregulation of angulin-1/LSR induced malignancy via upregulation of EGF-dependent CLDN-2 and TGF-β-dependent cell metabolism in human lung adenocarcinoma." (PMID 36961882, 2023). "In conclusion, downregulation of angulin-1/LSR induces malignancy via EGF-dependent claudin-2 and TGF-β-dependent cell metabolism in human lung adenocarcinoma." (PMID 36961882, 2023). "We have reported that SP-D directly binds to the N-glycans of EGFR, and downregulates the binding of EGF to EGFR and downstream signaling in human lung adenocarcinoma cells." (PMID 35089466, 2022). "It has been found that MAPK pathway inhibition prevents epidermal growth factor (EGF) and IFN-γ-induced PD-L1 expression in lung adenocarcinoma cells." (PMID 34439774, 2021). "In human lung adenocarcinoma A549 cells, MMP secretes epidermal growth factor, activates the EGFR-ERK signaling pathway, and promotes the expression of claudin-2, thus promoting tumor colonization (ciardiello and Tortora, 2008)." (PMID 34178945, 2021). "Concomitant with our results it was previously reported that both EGF and IFNγ induce CD274 expression in lung adenocarcinoma cells and act through the MAPK cascade, and imbalanced PD-1/PD-L1 interaction is observed during viral infections." (PMID 34045585, 2021). "In a representative lung adenocarcinoma cell line panel, stimulation with EGF or IFNγ increased CD274 mRNA and PD‐L1 protein and membrane levels, which were further enhanced by combining EGF and IFNγ." (PMID 30972766, 2019). "A recent study showed that SP-D reduced EGF -EGFR binding through the interaction between CRD of SP-D and N-glycans of EGFR, thus, leading to downregulation of EGF signaling in the A549 human lung adenocarcinoma cells." (PMID 31355132, 2019). "SP-D has recently been shown to inhibit the proliferation, migration and invasion of A549 human lung adenocarcinoma cells by binding to N-glycans of epidermal growth factor receptor (EGFR) via its CRD region, and interfering with EGF signaling." (PMID 31355132, 2019). "Epidermal growth factor (EGF) and its receptor (EGFR), which is most closely related to lung adenocarcinoma, were discovered by Stanley Cohen of Vanderbilt university in 1986." (PMID 30383772, 2018). "Lung adenocarcinoma A549 and CL1-1 cells cultured in serum-free medium supplemented with EGF and bFGF under suspension conditions initiated sphere formation at 5 days, and a continuous growth of the spheres until 12 days." (PMID 29416721, 2018). "Coimmunoprecipitation experiments in these and other lung adenocarcinoma cells confirmed that ERβ and EGFR interact in a gender-dependent manner and in response to E2 or EGF." (PMID 21951318, 2011). "After treatment with the PI3K inhibitor and EGF, the expression levels of E-cadherin and Vimentin recovered, indicating that LncRNA-AC009948.5 could promote EMT in lung adenocarcinoma cells through the PI3K/Akt/GSK3β signaling pathway." (PMID 36059662, 2022). "After treatment with the PI3K inhibitor and EGF, the expression of Snail decreased, indicating that LncRNA-AC009948.5 could promote Snail nuclear metastasis in lung adenocarcinoma cells through the PI3K/Akt/GSK3β signaling pathway." (PMID 36059662, 2022). "Indeed, EGF expression correlated with NRF2 activation in different cancer types, as we showed for NFE2L2/KEAP1 mutant lung adenocarcinoma as well as head and neck squamous cell carcinoma." (PMID 33916908, 2021).
lung adenocarcinoma (continued). "It was noteworthy that EGF triggered survival signaling and did not affect c-Src activity in lung adenocarcinoma cells." (PMID 34367939, 2021). "To further characterize the potential effects of PAbs we selected H292 lung adenocarcinoma cell line, which expresses intermediate levels of both receptors, and depends on EGF to growth (data not shown)." (PMID 29137309, 2017). "EGFR activation depended on EGF in the EGFR-nonaddictive lung adenocarcinoma." (PMID 34367939, 2021). "Exogenous SP-D treatment has been shown to downregulate epidermal growth factor (EGF) signaling by preventing the binding of EGF to the EGF receptor (EGFR), hence suppressing the cell proliferation, invasion, and migration of A549 human lung adenocarcinoma cells." (PMID 32733438, 2020). "In conclusion, MAPK pathway activity plays a key role in EGF‐ and IFNγ‐induced PD‐L1 expression in lung adenocarcinoma without targetable genetic alterations and may present a target to improve the efficacy of immunotherapy." (PMID 30972766, 2019). "Numerous reports indicate that growth factors, including TGF-β, epidermal growth factor (EGF), vascular endothelial growth factor, platelet-derived growth factor and hepatocyte growth factor can induce cancer cell EMT in a variety of cancers including lung adenocarcinoma." (PMID 24789104, 2014). "However, under conditions of growth factor-deprivation that yield cells sensitive to EGF (epidermal growth factor), IL-35 can inhibit expression of PD-L1+ in the ADC (lung adenocarcinoma) tumor cell line without impacting EGFR (epidermal growth factor receptor)." (PMID 34093586, 2021).
bladder cancer (65 papers, 1988 to 2025). "The epidermal growth factor system has been associated to prognosis in patients with bladder cancer based mainly on the expression of the epidermal growth factor (EGF) receptor 1 (EGFR) and HER2 and their activating ligands." (PMID 15583696, 2004). "Together with our discovery of TAK‐228‐induced EGF and IFNβ contributing to PD‐L1 upregulation in bladder cancer cells adds to understanding multiple mechanisms modulating PD‐L1 during mTOR inhibition by TAK‐228." (PMID 39258533, 2025). "In bladder cancer, SHCBP1 augments EGF-induced invasive behavior by associating with RACGAP1 and restricting the GTP hydrolysis activity of RAC1, a critical regulator of actin cytoskeleton dynamics and cell motility." (PMID 41009347, 2025). "Another targeted strategy was used to treat bladder cancer by fusing PA with epidermal growth factor (EGF), leveraging the high expression of EGFRs in bladder tumor cells." (PMID 41003524, 2025). "For the BLCA dataset, among the biomarkers identified from the SNV data, it has been revealed that EGF promotes bladder cancer cell proliferation via modulation of AR signals." (PMID 38678587, 2024). "Another proteomic biomarker discovery study in abundant-protein-depleted urine revealed the under expression of pro-epidermal growth factor (EGF) in the bladder cancer patient group vs. hernia patients." (PMID 37371512, 2023). "The motility and invasiveness of bladder cancer cells have been shown to be promoted by EGF stimulation." (PMID 35013128, 2022). "The EGF/EGFR ligand/receptor couple is frequently overexpressed in bladder cancers, with squamous bladder cancers qualified as being EGFR-addicted." (PMID 35740379, 2022). "These proteins are associated with inflammation (mediated by cytokines and chemokines) and signaling pathways related with bladder cancer proliferation (epidermal growth factor (EGF) and fibroblast growth factor (FGF) pathways)." (PMID 36148227, 2022). "Epidermal growth factor (EGF) has also been shown to promote the growth of bladder cancer cells via the AR pathway." (PMID 34064926, 2021). "The data suggest that TMEM97 expression is differentially regulated by EGF in different bladder cancer cell lines." (PMID 32668577, 2020). "Epidermal growth factor (EGF) induction of EMT in rat bladder carcinoma cells (NBT-II) was used as a model system." (PMID 30787030, 2019). "The EA influence on extracellular matrix invasion in response to VEGF-A or to EGF (a VEGFR-2 unrelated stimulus) by bladder cancer cells was tested in Boyden chambers endowed with filters coated with matrigel." (PMID 27879653, 2016). "It is well known that the EGF/EGFR pathway plays a critical role in bladder cancer development, progression and recurrence." (PMID 24801713, 2014). "There are several known markers used clinically for bladder cancer: nuclear matrix protein 22, telomerase, epidermal growth factor (EGF) receptor and others." (PMID 23374291, 2013). "To determine the role of cofilin phosphorylation in bladder cancer, we tested the effects of cofilin knockdown on EGF-induced migration of T24 human bladder cancer cells." (PMID 23374291, 2013). "Current results, thus, suggest that EGF promotes bladder cancer cell proliferation via modulation of AR signals." (PMID 22922989, 2012). "We next assessed the effect of EGF, in conjunction with androgen and/or antiandrogen, on AR transcriptional activity in bladder cancer cells." (PMID 22922989, 2012). "In vitro, MMP-1 production by bladder cancer cell lines can be stimulated by EGF; FGF-2 has also been shown to have an important regulatory role." (PMID 21941546, 2011). "The inhibition of EGF-R activity and EGF-mediated responses such as proliferation and cell motility has been reported for genistein in bladder cancer." (PMID 21941546, 2011). "In vitro, EGF-R overexpression increases bladder cancer cell motility, and EGF can stimulate cancer cell growth and proliferation, as well as invasion." (PMID 21941546, 2011).
bladder cancer (continued). "Despite the reported over-expression of EGFR in bladder cancer, leading to uncontrolled cell proliferation, increased angiogenesis and reduced apoptosis, to our knowledge, this is the first report regarding the expression of EGF in urinary bladder cancer." (PMID 21483670, 2011). "We next measured HB-EGF and EGF levels in urine specimens from the same Chinese IC patients, normal controls, bacterial cystitis patients and bladder cancer patients by ELISA." (PMID 15862132, 2005). "Also, dogs have been used to evaluate a novel EGF-anthrax toxin chimera developed for the treatment of bladder cancer." (PMID 40256602, 2025). "This hypothesis is consistent with ambrosin's inhibition of EGF-induced auto-phosphorylation of the critical Y1068 residue of EGFR in bladder cancer cells and, to a lesser extent, in triple negative breast cancer cells." (PMID 40754248, 2025). "EGF has been shown to promote bladder cancer cell proliferation." (PMID 38779086, 2024). "Moreover, the knockout of SHCBP1 reduced the migration and invasion ability in EGF-induced bladder cancer cells." (PMID 36920183, 2023). "Importantly, translocation of SHCBP1 to the nucleus induced by EGF treatment promoted the cell migration and invasiveness of bladder cancer cells in vitro and in vivo." (PMID 35013128, 2022). "Depletion of SHCBP1 reduces EGF-induced cell migration and invasiveness of bladder cancer cells." (PMID 35013128, 2022). "Herein, we wondered whether SHCBP1 responds to EGF/EGFR activation through translocation to the nucleus in bladder cancer." (PMID 35013128, 2022). "Similarly, integrin-mediated activation of Src in urinary bladder carcinoma cells leads to a phosphorylation pattern in the kinase domain of EGFR that is different from that induced by the binding of EGF to EGFR." (PMID 32458278, 2020). "Mesenchymal recurrent bladder cancer cells secreted multiple cytokines and growth factors, including transforming growth factor beta, interleukin-8, EGF, Wnt, and granulocyte-macrophage colony-stimulating factor, many of which are involved in malignancy progression in various types of carcinomas." (PMID 28423359, 2017). "It was further observed that EGF and CDH1 in the PPI network were annotated as being bladder cancer-associated proteins, and both receptor FGFR2 and PDGFRB could interact with EGF." (PMID 24801713, 2014). "Therefore, it appears that EGF is involved in bladder cancer cell invasion via cofilin phosphorylation." (PMID 23374291, 2013). "We also tested the induction of migration in response to EGF in T24 human bladder cancer cells." (PMID 23374291, 2013). "Knockdown of cofilin attenuated the EGF-induced migrations of T24 human bladder cancer cells." (PMID 23374291, 2013). "In bladder cancer cells, we here showed that EGF could activate AR transcription and PD168393, a specific inhibitor of EGFR, restored this EGF effect." (PMID 22922989, 2012). "The purpose of this study was to investigate the effects of EGF on AR activity in bladder cancer." (PMID 22922989, 2012). "In conclusion, EGF could increase AR transcriptional activity and cell proliferation in bladder cancer." (PMID 22922989, 2012). "We here found that TIF2 was considerably (e.g., ≥1.5-fold) augmented in the presence of EGF and DHT in bladder cancer cells, while EGF or DHT alone could lead to marginal/only slight increases in TIF2 expression." (PMID 22922989, 2012). "Although detailed mechanisms need to be clarified, these results may imply that elevated levels of TIF2 contribute to EGF/androgen-enhanced AR trans-activation in bladder cancer cells." (PMID 22922989, 2012). "In the present study, we provided evidence suggesting that EGF could regulate cell proliferation by activating AR signals in bladder cancer." (PMID 22922989, 2012). "Similarly, in bladder cancer lines 5637-AR and J82-AR where a wild-type AR was stably overexpressed, the effect of EGF was less significant than that of DHT." (PMID 22922989, 2012).
bladder cancer (continued). "This was supported by our observation that ETK activity could be stimulated by EGF, which was previously demonstrated to induce growth and enhance invasion of bladder cancer cells by regulating of AKT activity." (PMID 21408190, 2011). "Previous studies have indicated that the EGF system plays an important role in bladder cancer." (PMID 15583696, 2004). "However, the role of the EGF-SHCBP1 axis in bladder cancer progression remains unexplored." (PMID 35013128, 2022). "Thus, it is thought that EGF and its receptor play an important role in bladder cancer development." (PMID 27447744, 2016). "In the present study, we investigated whether EGF could alter AR activity in bladder cancer cells." (PMID 22922989, 2012). "In bladder cancer, nuclear translocation of SHCBP1 induced by EGF inhibits RACGAP1-mediated RAC1 inactivation to promote cancer cell proliferation and invasiveness." (PMID 40799237, 2025). "EGF stimulation increased the interaction between SHCBP1 and RACGAP1, which in turn attenuated the catalytic activity of RACGAP1 toward GTP-RAC1 in bladder cancer." (PMID 40789837, 2025). "In a COX2-overexpressed bladder cancer model, EREG is identified as the most highly expressed EGF, supporting tumor cell proliferation." (PMID 37020674, 2023). "In summary, our research has identified SHCBP1 as a new mediator of the crosstalk between EGF/EGFR signaling and RAC1 and a new mechanism mediating the progression of bladder cancer." (PMID 35013128, 2022). "A recent study has shown that the adaptor protein RacGAP1 inactivated GTP-bound Rac1 in bladder cancer, but the activation was inhibited by protein SHCBP1 (SHC-binding protein 1), which is a regulator of EGF (epidermal growth factor)." (PMID 35740379, 2022). "Our results showed that blockade of GTP-RAC1 using Ehop-016 inverses EGF-induced cell migration of 5637 cells expressing SHCBP1, indicating its positive effect on cell movement in bladder cancer, which is supported by other studies." (PMID 35013128, 2022). "Epidermal growth factor was reported to activate the androgen receptor and increase the expression of TRIP13 to promote bladder cancer progression." (PMID 34374227, 2021). "Using the human bladder cancer cell lines 5637 and T24, we isolated BCSCs by culturing 5637 or T24 cells in serum‐free DMEM/F12 (1:1) containing B27, recombinant EGF at 20 ng/mL and recombinant bFGF at 10 ng/mL." (PMID 30592142, 2019). "To identify the mechanisms through which HGF and its cognate receptor, c-MET, induces EMT in bladder cancer we treated the rat bladder carcinoma cell line NBT-II, with either HGF or EGF and analysed changes in cellular morphology with EMT marker expression." (PMID 31554791, 2019). "Accordingly, we select the intersection of two gene sets, namely the bladder cancer and PI3K–Akt pathways, which then generates four common genes, EGF, EGFR, THBS1, and VEGFA (EntrezGene ID: 1950, 1956, 7057, 7422)." (PMID 30868054, 2019). "More interestingly, EGF and DHT appeared to show synergistic effects on the proliferation as well as phosphorylation of EGFR, AKT, and ERK in bladder cancer cells." (PMID 28241422, 2017). "We reported here that in bladder cancer cells, KLF5-VEGFA axis was activated by growth factor EGF and bFGF, PKC agonist PMA and mitogenic lipid LPA, but inhibited by inhibitors of EGFR (AG1478), MEK1/2 (U0126) or PI3K (LY294002)." (PMID 26544730, 2015). "The finding supports the importance of the urinary EGF and urothelial EGFR interaction in the pathogenesis of human bladder cancer." (PMID 22991510, 2012). "A recent study shows that overactive Stat3 serves as the signal mediator between EGF and MMP-1 for bladder cancer cell migration, invasion and tumor formation." (PMID 18939995, 2008).